IL6 (interleukin 6)
Diseases named in the same sentence as IL6 in open-access papers (continued):
Sharing a sentence is not in itself a finding about the gene and the disease.
infection (continued). "High IL-6 levels promote the production of CRP in the liver, which is linked to infection, trauma, and cardiovascular and renal complications." (PMID 40572756, 2025). "This dampened immune response was corroborated in the serum levels of the cytokines IL-6 and IL-10 measured in both mouse strains, with C3 KO mice producing less of both cytokines at peak infection (day 3 post-infection) with Ig::Tn compared to WT B6 mice." (PMID 40586810, 2025). "Tumor necrosis factor-α (TNF-α), interleukin (IL)-1β, and IL-6 are cytokines produced by the immune system during the initial stages of infection." (PMID 40072101, 2025). "IL-6 and IL-8 levels have been shown to be rapidly released in response to infection often before the onset of clinical symptoms and before routine positive laboratory tests." (PMID 40171168, 2025). "We used Luminex profiling of serum taken at 6 days post infection in the high dose cohort to analyse the relative levels of 9 cytokines and chemokines: IL-1α, IL-1ß, IL-6, IL-10, IL-12(p70), IL-17, CCL2/MCP-1, GM-CSF and IFN-γ." (PMID 40587585, 2025). "Severe infection and clozapine itself can lead to alterations in interleukin-6, interleukin-1, interferon-ɣ and tumor necrosis factor-α leading to decreases in CYP1A2 and the body’s capacity to metabolize clozapine." (PMID 40704031, 2025). "Clinical variables associated with an adverse outcome were age, admission GCS, Rotterdam score, hospital infection, and levels of IL-6 on admission." (PMID 40713822, 2025). "This response involves the production of cytokines such as TNF-α, IL-1β, and IL-6, which recruit immune cells like neutrophils and macrophages to the site of infection." (PMID 39792889, 2025). "HsCRP is synthesized mainly by the liver upon response to IL-1 and IL-6 due to tissue infection or damage." (PMID 40283676, 2025). "In control macrophages, both HN878 and CDC1551 infections significantly increased the levels of proinflammatory (TNFα, IL1β, IL6, and CXCL8) and anti‐inflammatory (IL4 and IL10) molecules and GMCSF." (PMID 41287823, 2025). "Yet, IL-6 levels in the lung were significantly increased in Slc2a1-ΔGr mice at 40 h post-infection." (PMID 41226500, 2025). "The free vB-SeS-01 resulted in a significant reduction of the transcript levels of IL-6 and IL-8, both being reduced to one-fifth of the infection level." (PMID 39927265, 2025). "We infected PKR knock-out, human or European rabbit PKR-expressing HeLa cells with MYXV∆029L∆156R and analyzed TNFα and IL-6 expression 12 h after infection using qRT-PCR." (PMID 40872887, 2025). "A significant increase in IL‐6 after infection with A. fumigatus can affect immune cell function, and immune cell antiviral ability." (PMID 39865524, 2025). "We analysed mRNA expression of 9 inflammatory markers (TGF-β1, TNF-α, IL-1β, IFN-γ, IL-6, IL-23, IL-17a, iNOS and ColA1) in kidney of experimental mice at 15 days post infection." (PMID 40445994, 2025). "During the blood infection stage, pro-inflammatory cytokines such as IL-1β, IL-6, IL-8, IL-12, IFN-γ, and TNF-α released by the host immune system play a decisive role in antimalarial immunity by regulating immune cell activation and pathogen clearance." (PMID 41422632, 2025). "Both doses significantly activated the transcription of STAT1 and its downstream interferon-stimulated genes, while high-dose infection additionally triggered a cytokine storm characterized by excessive IL-6 and TNF-α expression." (PMID 40941331, 2025). "Blood IL-6 reflects the extent of systemic infection or inflammatory states, making it valuable in assessing the severity of infection and systemic inflammatory response." (PMID 40223136, 2025). "Compared to the GPS infection group, the expression of IL-6 in the 25 μg/mL baicalin group was significantly lower (p < 0.05), while the expressions of IL-1β and TNF-α were insignificantly lower (p > 0.05)." (PMID 40867785, 2025).
infection (continued). "In the early stages of infection, innate cytokines such as IL-1, IL-6, and TNF- α induce CRH secretion by neurons in the paraventricular nucleus (PVN) of the hypothalamus." (PMID 40176892, 2025). "IL-6 can be induced by the infection of the epithelium and upregulation of this cytokine has been observed by qRT-PCR in NiV infection." (PMID 40125323, 2025). "Exogenous IL-17A antagonized the increased mortality, suggesting that IL-6 is important for Th17 cell/IL-17A activation during PmA infection." (PMID 41402924, 2025). "Our findings suggest that the triggering and amplification of the antiviral pathways by IFN-γ and C/EBPβ/IL-6, respectively, conferred protection from infection of bystander CD4+ T cells upon ATI, resulting in the CA-vDNAlo phenotype." (PMID 40166014, 2025). "IL-6 facilitates a transient defense against infection or injury by alerting the immune system to the source of inflammation." (PMID 41041268, 2025). "In neonatal Swiss mice, USUV infection led to an increase in typical neuroinflammatory cytokines, including IL-6, CCL3, CCL4, CCL5, CXCL9, and CXCL10, with CXCL10 being upregulated to the highest level in this model." (PMID 39907280, 2025). "IL-6 plays a crucial role in host defense against infection and tissue injuries and is a bioindicator of multiple distinct types of cytokine storm." (PMID 40538651, 2025). "In the early stage of infection, ELISA results showed that exogenous PGD2 significantly promoted the secretion of TNF-α, IL-1β, and IL-6 in BMDMs and endometrial tissues, suggesting its role in enhancing the inflammatory response during early infection." (PMID 40874199, 2025). "SIDS cases with high IL-6 levels in cerebrospinal fluid and symptoms of mild infection prior to death also showed increased expression of both IgA and HLA-DR in the laryngeal mucosa." (PMID 40013115, 2025). "In particular, interleukin (IL)–6 is an endocrine factor that plays multiple roles in the response of the body to infection, exercise, and stress, as well as in inflammation." (PMID 41143503, 2025). "Cpn LPS can activate glial cells such as microglia and astrocytes, and in response to the infection, produce IL-6 to recruit even more glial cells to areas of infection." (PMID 40584180, 2025). "We found that 2.5 mg/kg M3 treatment greatly reduced proinflammatory cytokine (IL6, IFNγ, TNFα, and IL-1β) mRNA expression in the lung 3 days after infection, which explains the high efficacy of M3 in protecting mice from lethal IAV infection." (PMID 39601535, 2025). "Conversely, Pad2−/− mice showed a downregulation of M1‐related genes (Il1a, Il1b, Tnf, Cxcl2, Ccl4, Il12a, Cxcl1, Il6) compared to WT mice after PA infection." (PMID 40087815, 2025). "Results showed significant upregulation of TNF-α, IL-1β, IL-6, and IL-8 mRNA levels in Vero E6 cells post-infection." (PMID 40703674, 2025). "A wide range of cytokines, such as IL-3, IL-11, and granulocyte–macrophage colony-stimulating factors, as well as thrombopoietin and IL-6, are involved in stimulating platelet production in response to infection." (PMID 40427060, 2025). "IL-6 is rapidly secreted in response to infection or tissue injury, contributing to host defense by promoting acute-phase inflammation, while IL-8 promotes neutrophil recruitment, cell proliferation, and angiogenesis." (PMID 40725789, 2025). "In this model, TNF-α signaling was the most important upstream master regulator, because its blockade completely protected mice from lethal infection and suppressed the induction of most cytokines such as IL-1β, IL-17A, IL-6, and IL-12p70." (PMID 40127923, 2025). "The level of pro-inflammatory cytokine IL-6 changed after infection with both viruses compared to the mock." (PMID 40358160, 2025). "Serum protein levels of IL-1β (L), TNF-α (M), and IL-6 (N) were examined through ELISA assays 24 hr post infection." (PMID 39998486, 2025).
infection (continued). "On the 10th and 14th DPI, the infection with T. evansi induced a significant upregulation of IL-1β and IL-6 mRNA expression levels, whereas mRNA expression levels of TGF-β and IL-10 were downregulated in all infected groups when compared to the CN group." (PMID 40571943, 2025). "IL-6, a pleiotropic cytokine secreted by monocytes and macrophages, is pivotal in vascular inflammation and infection defense." (PMID 40453956, 2025). "Although previous studies have characterized the transcription of SAA, IL-1β, and IL-6 during Ich infection, their kinetics throughout the complete infection–recovery continuum remain uncharacterized." (PMID 40509043, 2025). "Stimulation of piglets with weaning stress or pathogen infection leads to increased expression and secretion of pro-inflammatory factors IL-6, TNF-α and IL-1β." (PMID 40351768, 2025). "Lower levels of PGE2, IL-1, IL-6, IL-8, and IL-17 in WT versus ΔeseG infection can lead to a less inflammatory environment, reducing neutrophil recruitment and macrophage activation (98, –, 100)." (PMID 40637600, 2025). "Upon infection of unvaccinated mice, the initial expression of Il6 on day 1 p.i. was upregulated, like that of Il6st, whereas that of Il6ra was significantly downregulated." (PMID 40243929, 2025). "We observed a robust cytokine response, including TNF-α, IL-6, G-CSF, and IL-1RA, peaking 6 h post-infection." (PMID 40766078, 2025). "For example, the regulation of IL-6 production and TNF signalling were intricately linked to infection, while IL-10 was associated with reduced severity." (PMID 40643149, 2025). "TNF-alpha and IL-6 are pivotal in mediating the body’s response to injury and infection and play complex roles in neural plasticity, brain function, and the pathophysiology of neurodegenerative diseases." (PMID 39906616, 2025). "Consistent with the bone measurement results, indole supplementation during ΔtnaA infection significantly elevated IL-1β, IL-6, and TNF-α levels in the gingival tissue of the Mutant + Indole group compared to the Mutant group." (PMID 40011497, 2025). "Pleural infection search terms were combined with “Interleukin-6 or IL-6 or Interleukin 6 or IL6” which identified 377 studies." (PMID 40819633, 2025). "Four weeks after BP-L1 infection, the level of pulmonary IL-6 was significantly higher than that of BP-L2 (P < 0.01) and CS (P < 0.001)." (PMID 40568708, 2025). "Future research on infection risk stratification in RSA should investigate the role of advanced biomarkers, including IL-6 and α-defensin." (PMID 40363957, 2025). "We additionally show B6 neutrophils can mitigate systemic inflammation in A/J mice as they preclude the dissemination of IL-6 early in infection." (PMID 39823516, 2025). "The main manifestations are dysregulation of T lymphocyte levels and elevated levels of infection-related biomarkers and inflammatory cytokines, including interleukin-1 (IL-1), interleukin-6 (IL-6), and tumor necrosis factor α (TNF-α)." (PMID 41156098, 2025). "Various cell signaling cytokines such as tumor necrosis factor-alpha (TNF-alpha), interferon-gamma (IFN-gamma), interleukin-6 (IL-6), and interleukin-10 (IL-10) are activated during infection, facilitating immune cell differentiation." (PMID 40086236, 2025). "The infection triggers a systemic inflammatory response, including elevated IL-6, TNF-α, and IL-1β, which amplifies vascular injury." (PMID 41012624, 2025). "SARS-CoV-2 spike protein at 12 μg/ml concentration showed robust release of IL-6 in infection group (around sixfold) when compared to the vaccination group." (PMID 40329195, 2025). "During hospitalization, infection-related indicators (white blood cell count, C-reactive protein, procalcitonin, and interleukin-6) all returned to normal ranges, and body temperature remained stable." (PMID 40980129, 2025). "Three days after H9N2 infection, IL-1β, IL-6, and IL-10 were more significantly increased in all test groups than in the control group (p < 0.05)." (PMID 40218416, 2025).
infection (continued). "In vivo and in murine organoids, the bladder mounts a rapid pro-inflammatory response to infection, including production of IL1β, IL-6, IL-8 (CXCL8), and TNF104,105." (PMID 40766562, 2025). "On the other hand, infection with SFV/TNFα specifically upregulated the amount of IL-6, CCL2, CCL3, CCL7 and CCL20 (p < 0.0001)." (PMID 40547518, 2025). "In contrast, CRP, a hepatic acute-phase protein stimulated predominantly by IL-6, demonstrates slower kinetics and remains elevated beyond infection control." (PMID 41281040, 2025). "CRP is an acute phase protein synthesized by the liver in response to pro-inflammatory cytokines (primarily interleukin-6) released during tissue injury, infection, or other inflammatory stimuli." (PMID 41153812, 2025). "As expected, pro-inflammatory cytokines like IL-6, IL-1β, and TNFα were upregulated during infection, while TNFα was higher in SCFM2-Scnn1b-Tg infected mice than SCFM2-C57BL/6 infected mice." (PMID 40512037, 2025). "The infection caused a robust but controlled immune response with elevated levels of MCP-1, TNF-α, and IL-6, that prevented severe neuronal damage." (PMID 41474758, 2025). "In this study, we observed that on the 10th day post-infection, the IL-6 levels in the lung homogenates of the LNP-mRNA group were significantly lower than those in the negative control group." (PMID 39831768, 2025). "Infection of the strain B10.O20 resulted in 15-350× increase of splenocytes’ production of IFNγ IL-2, IL-4, IL-6, IL-10 and IL-17." (PMID 41164189, 2025). "IL6 assists in providing temporary defense against infection or harm by notifying the immune system about the origin of inflammation." (PMID 39936078, 2025). "Our data revealed that the levels of most inflammatory cytokines, such as IL-8, IL-1β, IL-4, IL-6, and IL-2, etc., persistently increased with time during CV-A10 infection." (PMID 41165313, 2025). "Circulating levels of TNF-α, IL-1β, and IL-17a were elevated in mice infected with fas2Δ/Δ at 24 h post-infection compared to WT, whereas IFN-γ and IL-6 levels were significantly decreased but comparable to the saline (mock infection) control." (PMID 40138332, 2025). "In contrast, 20% TIL-L3 CFS + vitamin D significantly reduced infection-induced IL-6 production (p < 0.05), with vitamin D significantly improving CFS efficacy (p < 0.05)." (PMID 40351306, 2025). "Therefore, IL-6 could be a more suitable biomarker to assess a patient’s risk of infection on the first postoperative morning, leaving a clinically relevant time window for infection risk mitigation and surveillance." (PMID 40549692, 2025). "Locally, astrocytes and microglia express hepcidin in response to inflammatory cytokines such as IL-6 that activates the JAK/STAT3 signaling cascade to drive hepcidin transcription during infection or inflammation." (PMID 41007630, 2025). "To assess this, we measured levels of the pro‐inflammatory cytokines TNF‐α and IL‐6 at 24 h post‐infection." (PMID 40574345, 2025). "At lower concentrations, MRS-L3 CFS significantly inhibited IL-6 increase after infection (p < 0.05 for MRS-L3 CFS 10%, and p < 0.01 for 5%, compared to the infection control)." (PMID 40351306, 2025). "In bladder epithelial cells, R7 reduces infection with uropathogenic Escherichia coli and the upregulation of IL-6 expression after infection with these bacteria under high glucose conditions by regulating the JAK/STAT signaling pathway." (PMID 40461723, 2025). "Key cytokines such as interleukin-6 (IL-6), interleukin-8 (IL-8), and interleukin-10 (IL-10) are frequently studied for their roles in inflammation and infection." (PMID 40137168, 2025). "The dual properties of IL-6 reflect the disrupted inflammatory balance during infection, and its reduction after treatment indicates a regulatory effect." (PMID 40170927, 2025). "The levels of IL-1β in the two groups were comparable, whereas the level of IL-6 after infection was significantly lower in IFNAR1-/- mice than in WT mice." (PMID 40124358, 2025).
infection (continued). "MBIs affect the physiological markers integral to immune function, such as those involved in inflammation (like CRP and IL-6) and improve the response to infection." (PMID 40281902, 2025). "Our primary aim was to investigate postoperative hyperinflammation, assessed by maximum IL-6 concentrations, as an early predictor for infection after pulmonary cancer surgery." (PMID 40549692, 2025). "Consistent with clinical observations, in vitro infection of RD cells and in vivo infection of suckling mice in our study similarly demonstrated significant upregulation of IL-6, TNF-α, CXCL2, CXCL3, CXCL8 (IL-8), and CXCL10." (PMID 40872743, 2025). "Pooled evidence from 46 pediatric studies confirms that IL-6 and procalcitonin remain the most validated biomarkers for early infection detection in pediatric febrile neutropenia, though their clinical utility depends on rigorous contextual interpretation." (PMID 40647525, 2025). "Infection of Col1a1-K18-hACE2 KI mice induced high levels of IFNγ, IL-6, IP-10, MCP-1, and MIP-1β cytokines." (PMID 40272151, 2025). "It contributes to protection from infection, while the Th2 immune response, characterized by the production of IL-4, IL-10, TGF-β, IL-6, and others, is associated with disease progression and with parasite growth." (PMID 40666521, 2025). "During infection of LRSAM1-deficient cells, a significant increase in IL-6 secretion was observed compared to NTC cells." (PMID 40861495, 2025). "IL-6 is released in response to infection and is a potent inducer of acute phase response protein production in the liver." (PMID 41375563, 2025). "At 8 days post-infection, a significant 2-fold decrease in IL-6 levels was observed with the 10 and 100 μg/mL FGP treatments." (PMID 41155292, 2025). "The release of IL-6, a critical cytokine in inflammation and infection control, is part of the body’s defense mechanism against bacterial invasion and subsequent tissue damage." (PMID 40002706, 2025). "They all had low expression of interleukin (IL)‐6 in peripheral blood inconsistent with clinical infection symptoms." (PMID 40977416, 2025). "In conclusion, our current study revealed that Th17 cell/IL-17A is critical in the fight against PmA and that the IL-6–Jak2–Stat3 axis promoted Th17 cell/IL-17A activation during PmA infection in vivo." (PMID 41402924, 2025). "Offspring of both LFD- and HFD-fed dams exhibited reduced basal levels of key cytokines, including IL-6, IL-10, G-CSF, and GM-CSF, indicating a dampened innate immune system prior to infection." (PMID 40766470, 2025). "SAA1 and SAA2 are released into blood stimulated by IL-6 in response to infection, inflammation, injury, or stress." (PMID 40283676, 2025). "FluA infection triggers an excessive release of proinflammatory cytokines (e.g., IL-6, TNF-α, and IFN-γ), leading to a “cytokine storm,” a hallmark of systemic inflammation." (PMID 41321454, 2025). "Plasma IL-6 and CRP levels observed within 24 hours from the start of surgery are associated with postoperative infection risk, yet the added value of these biomarkers to a simple clinical prediction model seems limited." (PMID 40549692, 2025). "In the delicate balance of the neonatal immune system, IL-6 can influence clinical outcomes in various conditions, including infections, inflammatory diseases and other complications." (PMID 41302151, 2025). "TNF-α, IL-6, IL-8, and IL-1β showed higher levels in prolonged infection of HAO with rHPh-TX H5N1-Venus vs. pH1N1-mCherry." (PMID 40712003, 2025). "This pathway is associated with many immune function-related genes, and inflammatory genes such as IL-1β, IL-6, and IL-8 were significantly upregulated in the same infections." (PMID 40005807, 2025). "Conversely, 20% TIL-CFS significantly reduced IL-6 production upon infection (p < 0.01) and, when vitamin D was added, IL-6 levels were lower than both the infected control and the mock (p < 0.0001)." (PMID 40351306, 2025).